KCNK9 (potassium two pore domain channel subfamily K member 9)
Description:
K(+) channel that conducts voltage-dependent outward rectifying currents upon membrane depolarization. Voltage sensing is coupled to K(+) electrochemical gradient in an 'ion flux gating' mode where outward but not inward ion flow opens the gate. Changes ion selectivity and becomes permeable to Na(+) ions in response to extracellular acidification. Protonation of the pH sensor His-98 stabilizes C-type inactivation conformation likely converting the channel from outward K(+)-conducting, to inward Na(+)-conducting to nonconductive state. Homo- and heterodimerizes to form functional channels with distinct regulatory and gating properties (By similarity). Allows K(+) currents with fast-gating kinetics important for the repolarization and hyperpolarization phases of action potentials (By similarity). In granule neurons, hyperpolarizes the resting membrane potential to limit intrinsic neuronal excitability, but once the action potential threshold is reached, supports high-frequency action potential firing and increased neuronal excitability. Homomeric and/or heteromeric KCNK3:KCNK9 channels operate in cerebellar granule cells, whereas heteromeric KCNK1:KCNK9 enables currents in hippocampal dentate gyrus granule neurons (By similarity). Dispensable for central chemosensory respiration i.e. breathing controlled by brainstem CO2/pH, it rather conducts pH-sensitive currents and controls the firing rate of serotonergic raphe neurons involved in potentiation of the respiratory chemoreflex (By similarity). In retinal ganglion cells, mediates outward currents that regulate action potentials in response to acidification of the synaptic cleft. Involved in transmission of image-forming and nonimage-forming visual information in the retina (By similarity). In adrenal gland, contributes to the maintenance of a hyperpolarized resting membrane potential of aldosterone-producing cells at zona glomerulosa and limits aldosterone release as part of a regulatory mechanism that controls arterial blood pressure and electrolyte homeostasis (By similarity).
Synonyms: TASK3; K2p9.1; TASK-3; BIBARS; KT3.2; TASK32
Tractability: Small molecule: an approved drug acts on it; a structure with a bound ligand is known; a high-quality ligand is known; it belongs to a druggable protein family. Antibody: UniProt places it where antibodies can reach, with high confidence; its Gene Ontology location is reachable by antibodies, with high confidence; UniProt predicts a signal peptide or a membrane-spanning region; the Human Protein Atlas places it where antibodies can reach. PROTAC: a small molecule that binds it is known.
Target class: Two-pore domain potassium channel; Voltage-gated ion channel; Ion channel; Potassium channels
Chemical probes: ML308
Gene: Protein-coding gene on chromosome 8 (139,600,838 to 139,704,109, reverse strand). Ensembl gene ENSG00000169427.
Subcellular location: Cell membrane; Mitochondrion inner membrane; Cell projection, dendrite
Subcellular location (Human Protein Atlas): Plasma membrane
Pathways (Reactome):
Muscle contraction: Phase 4 - resting membrane potential
Neuronal System: TWIK-releated acid-sensitive K+ channel (TASK)
Gene Ontology:
Molecular function: identical protein binding; outward rectifier potassium channel activity; potassium channel activity; protein binding; protein heterodimerization activity; sodium channel activity; potassium ion leak channel activity; voltage-gated potassium channel activity
Biological process: cellular response to acidic pH; potassium ion import across plasma membrane; negative regulation of aldosterone secretion; potassium ion transport; regulation of action potential firing rate; regulation of resting membrane potential; visual perception; potassium ion transmembrane transport; sodium ion transmembrane transport
Cellular component: plasma membrane; mitochondrial inner membrane; dendrite; membrane; synaptic vesicle
Genetic constraint (gnomAD): Loss-of-function variants: 1 observed, 11.75 expected, observed/expected ratio (o/e) 0.0851, 90% interval 0.029 to 0.4. The upper end of that interval is the gene's LOEUF score, 0.4, which puts it in group 1 of 6, group 1 being the genes least tolerant of losing a copy. Missense variants: 142 observed, 308.68 expected, observed/expected ratio (o/e) 0.46, 90% interval 0.4 to 0.53. Synonymous variants: 127 observed, 136.05 expected, observed/expected ratio (o/e) 0.93, 90% interval 0.81 to 1.08.
Homologues: Orthologues: chimpanzee KCNK9 (100% identical), macaque KCNK9 (99% identical), dog KCNK9 (97% identical), pig KCNK9 (95% identical), tropical clawed frog kcnk9 (89% identical), rabbit KCNK9 (88% identical), guinea pig KCNK9 (85% identical), zebrafish kcnk9 (82% identical), rat Kcnk9 (73% identical), mouse Kcnk9 (72% identical), Drosophila melanogaster Task6 (45% identical), Drosophila melanogaster Task7 (41% identical), and 11 more. Paralogues in human: KCNK3 (58% identical), KCNK15 (50% identical), KCNK16 (24% identical), KCNK4 (23% identical), KCNK10 (22% identical), KCNK13 (22% identical), KCNK5 (22% identical), KCNK2 (21% identical), KCNK1 (21% identical), KCNK6 (21% identical), KCNK12 (20% identical), KCNK17 (20% identical), and 2 more.
Diseases named in the same sentence as KCNK9 in open-access papers:
KCNK9 is named in the same sentence as 88 diseases in open-access papers, as found by Europe PMC text mining. Sharing a sentence is not in itself a finding about the gene and the disease. The quoted sentences say what the papers report.
breast carcinoma (22 papers, 2009 to 2025). "Although KCNK9 was previously studied in association with breast cancer, our findings indicate its potential relevance to PC as well." (PMID 37787018, 2023). "We found that KCNK1 and KCNK9 were the two most common mutations in breast cancer, occurring in 21% and 18% of patients, respectively." (PMID 35656548, 2022). "KCNK1 and KCNK9 were the two most common mutations in breast cancer, occurred in 21% and 18% patients, respectively." (PMID 35656548, 2022). "We found that heterozygotes of OR8S1 rs11168618 (T/C) and EIF4A2 rs266719 (T/C) were negatively associated with breast cancer risk, whereas the heterozygote of KCNK9 rs2468677 (C/A) had an elevated risk." (PMID 34367982, 2021). "KCNK9 encodes for TASK3, a pH-regulated potassium channel membrane protein that is overexpressed in 40% of breast cancer." (PMID 34885139, 2021). "Altered TASK-3 expression has already been defined in several types of cancer, i.e., breast cancer, and the gene encoding TASK-3 (KCNK9) was found to be overexpressed by 5- to >100-fold in 44 % of tumors." (PMID 27289382, 2016). "The heterozygous CA genotype of KCNK9 rs2468677 (C/A) had increased breast cancer risk compared with the major AA genotype; however, it was found to be statistically significant only in model 2 with an additional adjustment for BMI (HR, 1.35; 95% CI, 1.00–1.80)." (PMID 34367982, 2021). "KCNK9 expression is also elevated in a number of breast cancer tumors, and experimentally overexpressing this channel promotes tumor formation in vivo." (PMID 38527087, 2024). "Expression of KCNK7 was negatively correlated with CD8+ T cell level, while KCNK9 expression was positively correlated with CD8+ T cell level in breast cancer." (PMID 35656548, 2022). "TASK-3 (also called KCNK9) is a member of the K2P potassium channel family, is overexpressed in a variety of tumor tissues such as breast cancer, gastric adenocarcinoma, ovarian cancer, and lung adenocarcinoma, and is closely related to tumor progression." (PMID 35251475, 2022). "We found that KCNK2 and KCNK5 was downregulated in breast cancer, while KCNK9, KCNK13, and KCNK15 was upregulated in breast cancer." (PMID 35656548, 2022). "Most promising, a recent study showed that antibodies targeting the KCNK9 protein inhibited 410.4 cell breast cancer cell metastasis in the mouse." (PMID 34885139, 2021). "This is the first identification of the KCNK9 DMR in mammary epithelial cells and demonstration that its hypomethylation in breast cancer is associated with increases in both mitochondrial membrane potential and apoptosis resistance." (PMID 34885139, 2021). "It has been reported that potassium channel subfamily K member 9 (KCNK9) is frequently overexpressed in breast cancer." (PMID 28974231, 2017). "Along those lines, K2P9.1, a two-pore domain potassium (K2P) channel, encoded by the KCNK9 gene, is overexpressed in lung and breast cancer." (PMID 27618016, 2016). "As we found relatively high KCNK9 expression in metastatic murine breast cancer cell lines, we went on to examine Y4's effects on metastasis." (PMID 26842342, 2016). "We found an inverse correlation between KCNK9 expression and overall survival of patients with either squamous cell lung or breast cancer (P<0.05)." (PMID 26842342, 2016). "In breast cancer patients, the 10-year relative survival rates of low KCNK9 expressers increased by 10% compared with high expressers." (PMID 26842342, 2016). "For example, KCNK9 (potassium channel subfamily K member 9) is overexpressed and contributes to tumorigenesis by promoting cancer cell survival in breast cancer." (PMID 23593331, 2013). "However, KCNK9 gene amplification accounts for increased expression in <10% of these breast cancers." (PMID 34885139, 2021). "KCNK9 hypomethylation was also found in non-cancerous tissue from 77% of women at high-risk of developing breast cancer." (PMID 34885139, 2021).
breast carcinoma (continued). "TASK3 is overexpressed in >40% of breast cancers, but genomic amplification of KCNK9 is reported to occur in <10% of breast cancers, indicating that epigenetic mechanisms may play a key role in TASK3 overexpression." (PMID 34885139, 2021). "KCNK9 hypomethylation was also found in non-cancerous tissue from women at high risk of developing breast cancer." (PMID 34885139, 2021). "Furthermore, KCNK9 is overexpressed in breast cancer, rectal cancer, melanoma, and adrenal cortical adenocarcinoma." (PMID 31581133, 2019). "Other type of K+ channel (KCNK9) was also shown to have oncogenic properties in breast cancer." (PMID 19640305, 2009). "Knockdown of KCNK9 inhibited cell proliferation and promoted cell cycle arrest and cellular senescence in the MDA-MB-231 breast cancer model." (PMID 40427758, 2025). "The RNA expression level of KCNK2, KCNK5, KCNK9, KCNK13, and KCNK15 were validated in human breast cancer cell lines." (PMID 35656548, 2022). "Overexpression of KCNK5, KCNK9, and KCNK12, as well as reduced expression of KCNK6 and KCNK15, was significantly correlated with triple-negative subtype in breast carcinoma." (PMID 35656548, 2022). "TASK3 is overexpressed in >40% of breast cancers, but genomic amplification of KCNK9 only accounts for TASK overexpression in <10% of breast cancers." (PMID 34885139, 2021). "Many studies have shown that potassium channels, including KCNN4, KCNA1, Kv11.1, KCNK9, KCNE1, and GIRK1 are involved in the regulation of malignant breast cancer transformation." (PMID 34195184, 2021). "Our results revealed that KCNK9, KCNK13, and KCNK15 was significantly upregulated in breast cancer cell lines including MDA-MB-231 and SK-BR-3 cell lines, while KCNK2 and KCNK5 was downregulated in breast cancer cell lines comparing with breast epithelial cell line MCF-10A." (PMID 35656548, 2022).
Birk-Barel syndrome (17 papers, 2014 to 2025). Birk-Barel syndrome is an inherited condition characterized by intellectual disability, hypotonia, hyperactivity, and unusual facial features. "KCNK9 (potassium channel subfamily K member 9) is a channelopathy protein associated with Birk-Barel syndrome." (PMID 38572415, 2024). "Particularly, in addition to the documented missense Kcnk9 mutations, the enhancer appears to be another target region for mutation and/or epigenetic alteration screening in patients with suspected Birk-Barel syndrome." (PMID 38297831, 2024). "A loss-of-function mutation in the imprinted KCNK9 locus was found to be related to the maternally inherited Birk-Barel syndrome, which is characterized by congenital hypotonia, variable cleft palate, delayed development, and feeding problems." (PMID 35482723, 2022). "Birk-Barel syndrome, alternatively known as KCNK9 imprinting syndrome, is caused by a missense mutation in the potassium two pore domain channel subfamily K member 9 (KCNK9) gene on chromosome 8q24.3." (PMID 34327088, 2021). "Heterozygous mutations in the KCNK9 gene on the maternal allele led to Birk-Barel syndrome (BBS; OMIM 612292)." (PMID 33316910, 2020). "Birk Barel mental retardation dysmorphism syndrome is caused by a missense mutation in the maternal copy of KCNK9 gene which encodes for TASK-3 (K2P9.1)." (PMID 31031627, 2019). "Heterozygous KCNK9 mutations are associated with the imprinting disorder Birk-Barel syndrome." (PMID 33316910, 2020). "Imprinting of the KCNK9 gene is associated with Birk Barel syndrome." (PMID 29055033, 2017). "Here, we resolve structures for both human TASK-1 and TASK-3 by cryoEM, as well as for a recurrent TASK-3 variant (G236R) associated with KCNK9 Imprinting Syndrome (formerly referred to as Birk-Barel Syndrome)." (PMID 39637865, 2025). "KCNK9 imprinting syndrome (KIS), also known as Birk-Barel syndrome (MIM: 612292), is a rare genetic disorder caused by a genetic alteration of the maternal copy of KCNK9, first reported with the causal variant, p.(Gly236Arg), and two subsequent variants of uncertain significance (VUS)." (PMID 35698242, 2022). "Targeted massive parallel sequencing did not reveal the KCNK9 mutations associated with Birk-Barel syndrome." (PMID 33316910, 2020). "In a single report, familial Birk Barel syndrome that is characterized by mental retardation, hypotonia, and facial and skeletal dysmorphism is caused by a mutation in the paternally imprinted potassium channel TASK-3 (KCNK9) on chromosome 8q24.3." (PMID 24972929, 2014).
melanoma (14 papers, 2013 to 2026). A malignant, usually aggressive tumor composed of atypical, neoplastic melanocytes. "Base on the previous research, KCNK9 was overexpressed in rectal cancer, melanoma, and adrenal cortical adenocarcinoma." (PMID 35656548, 2022).
epilepsy (5 papers, 2021 to 2025). A brain disorder characterized by episodes of abnormally increased neuronal discharge resulting in transient episodes of sensory or motor neurological dysfunction, or psychic dysfunction. "Additionally, a number of VGKCs including KCNB2, KCNF1, KCNK6, KCNK9 and KCNJ5 are significantly upregulated in the NRXN1α+/- transcriptome, and gain of function of VGKCs has been identified in neurodevelopmental disorders including epilepsy." (PMID 34525970, 2021). "Thus, the combined decreased expression of Kcna3 (Kv1.3), Kcnk9 (TASK3), Kcnn3 (SK3), Kcng3 (Kv7.3), and Kcns3 (Kv9.3) around day 8 could lead to increased chances of persistent membrane depolarization, which ultimately may lead to epilepsy." (PMID 34877936, 2021).
lung carcinoma (5 papers, 2016 to 2020). "The potassium channel KCNK9 mediates important biological processes and is often overexpressed in breast and lung cancers." (PMID 26842342, 2016). "High-resolution mapping of an amplicon in human breast and lung cancers identified KCNK9 as the only gene with genomic amplifications." (PMID 26842342, 2016).
triple-negative breast carcinoma (5 papers, 2018 to 2025). An invasive breast carcinoma which is negative for expression of estrogen receptor (ER), progesterone receptor (PR), and human epidermal growth factor receptor 2 (HER2). "Maternal germline inactivation of the maternally expressed allele of KCNK9 results in Birk–Barel syndrome, and KCNK9 loss of imprinting is also prevalent in triple-negative breast cancer." (PMID 40613785, 2025). "Hypomethylation at the DMR, coupled with biallelic expression of KCNK9, occurred in 63% of triple-negative breast cancers (TNBC)." (PMID 34885139, 2021). "In triple-negative breast cancer (TNBC), the LOI of potassium two-pore domain channel subfamily K member 9 (KCNK9) gene involving differentially methylated region (DMR) hypomethylation leads to overexpression of the gene, increasing mitochondrial membrane potential and anti-apoptotic effect." (PMID 38812777, 2024).
breast tumors (4 papers, 2009 to 2022). "In light of recent studies, this is an extremely interesting observation, as the expression of the KCNK9 gene for TASK-3 channels is increased in human breast tumors and lung tumors and in 90% of ovarian tumors." (PMID 35011530, 2022). "Another member of this family, TASK3 or KCNK9, was also amplified and showed elevated expression in breast tumors." (PMID 21637642, 2009).
depression (4 papers, 2021 to 2023). "Mice lacking TASK3 (Kcnk9-/-) have impaired memory, sleep perturbation, and resistance to despair behavior that has a link to depression." (PMID 35698242, 2022).
gastric cancer (4 papers, 2019 to 2025). A primary or metastatic malignant neoplasm involving the stomach. "In addition, KCNK9 was found to promote migration and survival in gastric cancer cell lines and was upregulated in an animal model of oral squamous cell carcinoma." (PMID 40427758, 2025).
oral squamous cell carcinoma (3 papers, 2022 to 2025). "In clinical cancer, KCNK9 and KCNK18 (TRESK) were downregulated in advanced oral squamous cell carcinoma, in contrast to the findings of the animal study." (PMID 40427758, 2025).
channelopathies (2 papers, 2022 to 2024). "The current study makes significant contribution to the understanding of the field of channelopathies in general and to KIS, in particular, by characterizing a sizable cohort of individuals with novel genetic variants in KCNK9 affected with this neurodevelopmental syndrome." (PMID 35698242, 2022).
hepatocellular carcinoma (2 papers, 2023 to 2025). A malignant tumor that arises from hepatocytes. "The prognostic and diagnostic capabilities of KCNK9 for Hepatocellular Carcinoma (HCC) have been examined." (PMID 36905879, 2023).
Obesity (2 papers, 2018 to 2024). Accumulation of substantial excess body fat. "A great deal of studies has shown that KCNK9 gene is associated with obesity, HDL-C, adiponectin levels and aldosterone production." (PMID 30498476, 2018).
scoliosis (2 papers, 2020 to 2024). A congenital or acquired spinal deformity characterized by lateral curvature of the spine. "Disruptions in another potassium channel called Task3 (KCNK9) are associated with scoliosis, cleft palate and other characteristic facial features." (PMID 32581710, 2020). "Similarly, disruptions in the TASK3 potassium channel, also known as KCNK9, have been linked to conditions such as scoliosis, cleft palate and distinctive facial features in humans." (PMID 38736327, 2024).